TMEM120B (transmembrane protein 120B)
Description:
Necessary for efficient adipogenesis. Does not show ion channel activity.
Tractability: Antibody: UniProt predicts a signal peptide or a membrane-spanning region. PROTAC: ubiquitination databases record sites on it.
Gene: Protein-coding gene on chromosome 12 (121,712,752 to 121,783,001, forward strand). Ensembl gene ENSG00000188735.
Subcellular location: Nucleus inner membrane
Subcellular location (Human Protein Atlas): Nucleoli fibrillar center; Cytosol
Gene Ontology:
Molecular function: protein binding; monoatomic ion channel activity
Biological process: fat cell differentiation; protein heterooligomerization
Cellular component: nuclear inner membrane; membrane
Genetic constraint (gnomAD): Loss-of-function variants: 28 observed, 46.44 expected, observed/expected ratio (o/e) 0.6, 90% interval 0.45 to 0.83. The upper end of that interval is the gene's LOEUF score, 0.83, which puts it in group 3 of 6, group 1 being the genes least tolerant of losing a copy. Missense variants: 369 observed, 402.46 expected, observed/expected ratio (o/e) 0.92, 90% interval 0.84 to 1. Synonymous variants: 195 observed, 171.64 expected, observed/expected ratio (o/e) 1.14, 90% interval 1.01 to 1.28.
Homologues: Orthologues: macaque TMEM120B (99% identical), rat Tmem120b (95% identical), mouse Tmem120b (94% identical), dog TMEM120B (94% identical), guinea pig TMEM120B (93% identical), chimpanzee TMEM120B (86% identical), pig TMEM120B (85% identical), zebrafish tmem120b (78% identical), tropical clawed frog tmem120b (76% identical), Drosophila melanogaster CG32795 (47% identical), Caenorhabditis elegans tmem-120 (43% identical). Paralogues in human: TMEM120A (70% identical).
Diseases named in the same sentence as TMEM120B in open-access papers:
TMEM120B is named in the same sentence as 20 diseases in open-access papers, as found by Europe PMC text mining. Sharing a sentence is not in itself a finding about the gene and the disease. The quoted sentences say what the papers report.
lung carcinoma (2 papers, 2022 to 2024). "Most of these sites are located in genes that have been well-established to be implicated in lung cancer development except TMEM120B and ZNF440." (PMID 35768804, 2022).
Obesity (2 papers, 2017 to 2018). Accumulation of substantial excess body fat. "In PCOS, up-regulated TMEM120B will promote adipocyte differentiation/metabolism and induce obesity." (PMID 30075721, 2018).
breast carcinoma (1 paper, 2024). "Overexpression of TMEM120B promoted breast cancer cell proliferation, invasion, and stemness by activating TAZ-mTOR signaling." (PMID 38504374, 2024). "We examined the expression and subcellular localization of TMEM120B in seven breast cancer cell lines and one normal breast cancer cell line (MCF-10 A)." (PMID 38504374, 2024). "Next, we explored the mechanism by which TMEM120B promoted breast cancer cell proliferation, invasion, and metastasis." (PMID 38504374, 2024). "IHC staining was performed to explore the correlation between TMEM120B expression and its downstream factors in human breast cancer samples." (PMID 38504374, 2024). "Immunofluorescence staining also indicated that TMEM120B exhibited both cytosolic and nuclear localization in breast cancer cell lines." (PMID 38504374, 2024). "Both the first and second rounds of sphere formation assays suggested that the stemness of breast cancer cells was enhanced or abrogated after the overexpression or depletion of TMEM120B in MCF-7 and SK-BR-3 or MDA-231 and MDA-453 cells, respectively." (PMID 38504374, 2024). "IHC staining indicated that TMEM120B was expressed mainly in the cytosol and fewly in the nucleus of breast cancer cells." (PMID 38504374, 2024). "TMEM120B expression was elevated in breast cancer patients with poor treatment outcomes (Miller/Payne grades 1–2) than in those with better outcomes (Miller/Payne grades 3–5)." (PMID 38504374, 2024). "Western blot analysis indicated that TMEM120B expression was higher in all detected breast cancer cell lines than in MCF-10 A cells." (PMID 38504374, 2024). "We explored the signaling pathway transduction upon TMEM120B overexpression to maintain the stemness of breast cancer cells." (PMID 38504374, 2024). "Our study revealed that TMEM120B was highly expressed in breast cancer and other malignant carcinomas, and its expression was significantly correlated with advanced TNM stage, positive lymph node metastasis, and poor prognosis." (PMID 38504374, 2024). "Overexpression of TMEM120B may strengthen breast cancer stemness via the β1-integrin-FAK-TAZ-mTOR signaling axis by binding to MYH9." (PMID 38504374, 2024). "Interestingly, bioinformatics analysis indicated that TMEM120B expression was significantly positively correlated with breast cancer stemness." (PMID 38504374, 2024). "Finally, we overexpressed TMEM120B, TMEM120B-∆CCD, MYH9, MYH9-∆CCD alone or co-transfected TMEM120B + MYH9, TMEM120B-∆CCD + MYH9, and TMEM120B + MYH9-∆CCD into breast cancer cells." (PMID 38504374, 2024). "Further, we assessed the effects of limiting dilution xenograft on breast cancer stemness upon TMEM120B depletion in MDA-MB-231 cells in vivo, which also indicated that overexpression of TMEM120B may strengthen breast cancer stemness." (PMID 38504374, 2024). "Flow cytometry also indicated that the ratio of ALDH1-positive cells elevated more than the other groups upon co-transfecting TMEM120B + MYH9.Our results indicated that the TMEM120B–MYH9 interaction may enhance breast cancer stemness by activating the β1-integrin-FAK-TAZ-mTOR signaling axis." (PMID 38504374, 2024). "TMEM120B accelerated the cycling of β1-integrin and the assembling of FAs by activating the TAZ-mTOR signaling axis via binding to MYH9 through its coil-coil domain, thus strengthening proliferation and invasion, maintaining the stemness of breast cancer cells, and promoting chemoresistance." (PMID 38504374, 2024). "However, our results suggested that TMEM120B is mainly localized in the cytoplasm of breast cancer cells rather than in the nuclear lamina.To further explore the biological roles of TMEM120B within diverse subcellular localization." (PMID 38504374, 2024). "However, Cox univariate analysis revealed that TMEM120B expression was not an independent prognostic factor in patients with breast cancer." (PMID 38504374, 2024).
breast carcinoma (continued). "First, we used The Cancer Genome Atlas (TCGA) database to explore the mRNA expression of TMEM120B in pan-cancer and normal tissues and found that TMEM120B was highly expressed in most cancerous tissues than in non-cancerous ones; however, breast cancer was excluded." (PMID 38504374, 2024). "Whereas it reveal no obvious differences for TMEM120B RNA among diverse subtypes of breast cancer.Kaplan–Meier analysis revealed that both TMEM120B mRNA and protein levels were higher in patients with a poor prognosis than better ones (P = 0.095 and P = 0.079)." (PMID 38504374, 2024).
fibrosarcoma (1 paper, 2015). A malignant mesenchymal fibroblastic neoplasm affecting the soft tissue and bone. "For this, TMEM120B was exogenously expressed as a fusion to GFP and transfected into HT1080 human fibrosarcoma cells." (PMID 26024229, 2015).
glioma (1 paper, 2014). A benign or malignant brain and spinal cord tumor that arises from glial cells (astrocytes, oligodendrocytes, ependymal cells). "In TMEM120B, a gene with an unclear function, the mutation COSM1599921 has been previously detected in glioma." (PMID 25496518, 2014).
lung squamous cell carcinoma (1 paper, 2023). "TMEM120B, HMOX2, CALCOCO2, LONP2, ZNF440, CLCC1, and CHMP3 were identified to be optimal prognostic factors for lung squamous cell carcinoma (LUSC)." (PMID 36999050, 2023).
lymph node metastasis (1 paper, 2024). "TMEM120B expression positively correlated with advanced TNM stage, lymph node metastasis, and poor prognosis." (PMID 38504374, 2024). "Our study demonstrated that TMEM120B was highly expressed in the cytoplasm and was correlated with advanced TNM stage, lymph node metastasis, and poor prognosis." (PMID 38504374, 2024).
osteosarcoma (1 paper, 2022). A usually aggressive malignant bone-forming mesenchymal neoplasm, predominantly affecting adolescents and young adults. "Prognosis-related TMEM protein family genes were identified by the univariate Cox regression analysis and were utilized to construct a signature based on six TMEM protein family genes (TMEM120B, TMEM147, TMEM9B, TMEM8A, TMEM59, and TMEM39B) in osteosarcoma." (PMID 35991561, 2022).
ovarian carcinoma (1 paper, 2024). A malignant neoplasm originating from the surface ovarian epithelium. "Both bioinformatics analysis and immunohistochemistry assays were performed to examine expression patterns of TMEM120B in lung, breast, gastric, colon, and ovarian cancers." (PMID 38504374, 2024). "TMEM120B expression was elevated in lung, breast, gastric, colon, and ovarian cancers." (PMID 38504374, 2024).
primary open-angle glaucoma (1 paper, 2022). "Besides, TMEM120B protein was significantly altered in the aqueous humor of patients with primary open-angle glaucoma." (PMID 35991561, 2022).
tumor (3 papers, 2014 to 2024). "Additionally, xenograft assays revealed that tumor volumes significantly increased in SK-BR-3 cells overexpressing TMEM120B, whereas the number of lung metastases visibly increased in the ectopic TMEM120B group, however there were no obvious changes in metastasis of liver, brain, kidney and heart." (PMID 38504374, 2024). "Interestingly, significantly negative correlations between chr12:122215052A > I level and TMEM120B expression, chr19:11945758A > I level and ZNF440 expression, chr1:109474650A > I level and CLCC1 expression, chr16:48388244A > I level and LONP2 expression, were observed in LUSC tumor tissues." (PMID 35768804, 2022).
cancer (2 papers, 2022 to 2024). A tumor composed of atypical neoplastic, often pleomorphic cells that invade other tissues. "However, the exact function of TMEM120B in malignant tumors required further exploration." (PMID 35991561, 2022). "However, to date, the expression patterns and biological functions of TMEM120B in human tissues, especially in malignant tumors, have not been reported." (PMID 38504374, 2024).
TMEM120B also shares sentences with these, for which no sentence is quoted: colon cancer (1 paper); dyslipidemia (1); gastric carcinoma (1); Hypertension (1); malignant carcinomas (1); metabolic disorders (1); prostate adenocarcinoma (1); triple-negative breast carcinoma (1).